RBM4B (RNA binding motif protein 4B)
Description:
Required for the translational activation of PER1 mRNA in response to circadian clock. Binds directly to the 3'-UTR of the PER1 mRNA (By similarity).
Synonyms: RBM30; MGC10871; ZCCHC15; RBM4L; ZCRB3B; ZCCHC21B
Tractability: PROTAC: ubiquitination databases record sites on it; its protein half-life has been measured.
Gene: Protein-coding gene on chromosome 11 (66,664,996 to 66,677,925, reverse strand). Ensembl gene ENSG00000173914.
Subcellular location: Nucleus; Nucleus, nucleolus
Subcellular location (Human Protein Atlas): Nucleoplasm; Cytosol
Gene Ontology:
Molecular function: protein binding; RNA binding; nucleic acid binding; zinc ion binding
Biological process: circadian regulation of gene expression; circadian rhythm; entrainment of circadian clock by photoperiod; regulation of alternative mRNA splicing, via spliceosome; regulation of translation
Cellular component: protein-containing complex; nucleolus; nucleus
Genetic constraint (gnomAD): Loss-of-function variants: 13 observed, 29.7 expected, observed/expected ratio (o/e) 0.44, 90% interval 0.28 to 0.7. The upper end of that interval is the gene's LOEUF score, 0.7, which puts it in group 2 of 6, group 1 being the genes least tolerant of losing a copy. Missense variants: 387 observed, 500.15 expected, observed/expected ratio (o/e) 0.77, 90% interval 0.71 to 0.84. Synonymous variants: 167 observed, 181.65 expected, observed/expected ratio (o/e) 0.92, 90% interval 0.81 to 1.04.
Homologues: Orthologues: chimpanzee RBM4B (100% identical), macaque RBM4B (100% identical), dog RBM4B (99% identical), guinea pig RBM4B (98% identical), mouse Rbm4b (96% identical). Paralogues in human: RBM4 (90% identical), A1CF (21% identical), RBMX (21% identical), RBMXL1 (21% identical), TIA1 (20% identical), DAZAP1 (19% identical), RBM19 (19% identical), RBM47 (19% identical), TIAL1 (19% identical), HNRNPA3 (19% identical), HNRNPA2B1 (18% identical), MSI1 (18% identical), and 24 more.
Diseases named in the same sentence as RBM4B in open-access papers:
RBM4B is named in the same sentence as 3 diseases in open-access papers, as found by Europe PMC text mining. Sharing a sentence is not in itself a finding about the gene and the disease. The quoted sentences say what the papers report.
heart failure (1 paper, 2024). Inability of the heart to pump blood at an adequate rate to meet tissue metabolic requirements. "Furthermore, the 3-fold upregulation of the RNA binding motif protein 4B (RBM4) examplifies the significant genomic responses with its reactivation in heart failure driving the transcriptome into a fetal state." (PMID 39285385, 2024).
RBM4B also shares sentences with these, for which no sentence is quoted: amnesia (1 paper); infection (1).